CD5 (CD5 molecule)
Diseases named in the same sentence as CD5 in open-access papers (continued):
Sharing a sentence is not in itself a finding about the gene and the disease.
lupus (22 papers, 2013 to 2025). "Treatment with IL-35 significantly increased the numbers of IL-10-secreting CD1d+CD5+ Bregs and ameliorated renal damages in lupus-prone MRL/Lpr mice." (PMID 31795353, 2019). "Although short-lived plasmablasts are a primary source of autoantibodies in various lupus mouse models, CD5+ B cells or B1-like cells have also been characterized as possible producers of autoantibodies." (PMID 28741259, 2017). "Early reports have found increased CD5+ B cells in patients with rheumatoid arthritis (RA), Sjögren's syndrome and systemic lupus erythematosus (SLE)." (PMID 27014914, 2016). "In some lupus patients, an alternative promoter becomes demethylated leading to a switch from the CD5-E1A isoform normally found at the cell surface to the CD5-E1B isoform that is retained in the cytoplasm resulting in a failure to suppress autoreactivity." (PMID 25763008, 2015). "Recently, circulating CD5 levels were shown to be increased in RA and systemic lupus erythematosus, and currently we have confirmed the elevation of its ligand, CD5L, in PsA SF." (PMID 25097465, 2014). "Subsequently, hypomethylation of certain genes have been identified as important in lupus T cells, such as ITGAL (CD11a), CD40LG (CD40L), TNFSF7 (CD70), Killer-cell immunoglobulin-like receptor (KIR2DL4), perforin (PRF1), and CD5 in lupus B cells." (PMID 25566322, 2014). "One possible explanation for the results of increased frequencies of CD5+CD1dhiCD19+ B cells in the context of the pristane lupus model has to do with the low proportion and numbers of peritoneal pDCs, and the decreased levels of IFN-α in Cd38−/− mice 2 weeks after pristane treatment." (PMID 30257456, 2018). "Furthermore, hypomethylation of HERV-E in the flanking promoter region of the CD5 gene in lupus has been found to increase CD5-E1B isotype in lupus B cells." (PMID 28785369, 2017). "Given the recent interest in regulatory B cells, we hypothesized that IL-10 production by CD5+ B cells was critical to suppression in our lupus-prone mice." (PMID 26964093, 2016). "One study revealed that CD163+CD14+ DC3s were significantly increased within the CD5− DC subset exclusively in systemic lupus erythematosus (SLE) patients which correlated with disease severity." (PMID 40584260, 2025). "Both lupus patients and aged BWF1 mice have increased CD5+ B cells in their blood, which has been directly correlated with an increase in autoantibodies." (PMID 28741259, 2017). "Dex drug and W treatment did not affect Tregs (CD4+ CD25+ FOXP3+) and Bregs (CD5+ CD1d+) in lupus mice." (PMID 40158179, 2025). "The minor cluster #11 expressed AXL, IRF4, IRF7, and CD5 genes previously found in AS-DC, Pre-DC, or pDC45,46, but was absent from blood samples; #11 better aligned to transitional DC47 and were mostly observed in HNSCC and in Lupus." (PMID 35418195, 2022). "In CD5+ B-1 cells obtained from aged male ApoE knockout mice, the most frequently utilized CDR-H3 is AGDYDGYWYFDV (VH12/DH2/JH1), which is the same frequently utilized CDR-H3 seen in the lupus-prone mice." (PMID 36713434, 2022). "Furthermore, when the spleen cells from lupus mice (MRL/lpr mice) were cultured with PD-L1 positive MDSCs, only PD-L1 positive MDSCs form control mice remarkably suppressed plasma cell (CD19-CD138+) population and expanded IL-10 producing B 10 cell (CD19+CD5+CD1d+)." (PMID 33986739, 2021). "Expression of p-STAT3 and STAT3 proteins was detected at higher levels in sorted CD19+CD5+CD1dhigh B cells from MRL/lpr mice than in sorted cells from B6 mice, and this finding suggests that activation of STAT3 may contribute to the expansion of B10 cells in lupus-prone MRL/lpr mice." (PMID 23638156, 2013).
marginal zone lymphoma (19 papers, 2012 to 2025). A usually indolent mature B-cell lymphoma, arising from the marginal zone of lymphoid tissues. "Nodal, splenic, and MALT marginal zone lymphomas correspond to memory B cells (CD5− CD10−) in the post-germinal center maturation phase." (PMID 38534887, 2024). "However we should take into account that although most marginal zone lymphoma clones are CD5(−), occasionally CD5 is positive." (PMID 25295254, 2014). "Flow cytometry showed an abnormal kappa‐restricted population (bottom right) of CD5‐variable CD10‐negative B cells phenotypically consistent with marginal zone lymphoma (MZL)." (PMID 41262227, 2025). "However, CD5-postive marginal zone lymphomas have been reported." (PMID 26201725, 2015). "Differential diagnosis for marginal zone B cell lymphoma mainly depends on immunohistochemistry, including at least CD20, CD10, CD5, CD23, cyclin D1, immunoglobulin D, and SOX11." (PMID 36973717, 2023). "Three distinct subtypes based on immunotypic features have been identified: CLL-like MBL (CD19+, CD20dim, CD5+, CD20+, surface Igdim, FMC7-), atypical CLL-like MBL (CD19+, CD20bright, CD5+, CD23-, FMC7+/-), and CD5- MBL which resembles marginal zone lymphoma." (PMID 36599826, 2023). "CD5(−) MBL is characterized by an immunophenotype consistent with marginal zone origin and displays many similarities with marginal zone lymphomas (MZL), mainly the splenic MZL." (PMID 25295254, 2014). "Thus, using SOX11 as a diagnostic marker for MCL avoids misclassification of morphologically similar CD5+ marginal zone lymphomas (MZL) or CD23- chronic lymphocytic leukemia (CLL)." (PMID 22738398, 2012). "In most CD5(−) MBL cases, clonal B cells display either an unclassifiable or a marginal zone lymphoma- (MZL-) like immunophenotype." (PMID 25295254, 2014). "Those with a B-CLPD that does not express CD5 will usually be found to have the leukemic phase of a well-defined lymphoma such as marginal zone lymphoma (MZL), lymphoplasmacytic lymphoma (LPL), follicular cell lymphoma (FCL), or hairy cell leukemia (HCL)." (PMID 31803290, 2012).
thymoma (19 papers, 2007 to 2025). A neoplasm arising from the epithelial cells of the thymus. "Seventeen cases (100%) and 16 cases (94.1%) of TSCC were CD117 and CD5 positive, and 1 (0.9%) case of B3 thymoma was double positive for CD5 and CD117." (PMID 36088333, 2022). "Although the percentage of CD70 positive cells in each case was rather small, the sensitivity and specificity of CD70 in distinguishing TSCC from thymoma are comparable with those of CD5 and CD117." (PMID 35145909, 2021). "Previous studies showed that 0–7% and 0–18% of thymoma were positive for CD5 and CD117, respectively." (PMID 35145909, 2021). "KIT and CD5 were positive in 17 (100%) and 16 (94.1%) TSQCCs, whereas one (0.9%) type B3 thymoma showed double positivity for KIT and CD5." (PMID 32704057, 2020). "Briefly, KIT and CD5 are positive in ~ 80% of TSQCCs, whereas ~ 3% of thymomas show positivity for KIT or CD51,4." (PMID 32704057, 2020). "KIT and CD5 were positive in 17 (100%) and 16 (94.1%) TSQCCs, respectively, whereas one (0.9%) type B3 thymoma showed double positivity for KIT and CD5." (PMID 32704057, 2020). "The pattern of CD99 and TdT immunostaining was similar to that of CD1α, CD3 and CD5 in type AB thymoma and squamous cell carcinoma." (PMID 28095872, 2017). "Two of seventeen (11.7%) thymomas (all sporadic B3 type) contained numerous neoplastic epithelial cells positive for CD5 and bcl-2." (PMID 17498299, 2007). "Two of seventeen (11.7%) thymomas (all sporadic B3 type) contained numerous CD5+ and bcl-2+ neoplastic epithelial cells." (PMID 17498299, 2007). "Two of seventeen (11.7%) thymomas (all sporadic type B3) contained numerous CD5+, bcl-2+ neoplastic epithelial cells." (PMID 17498299, 2007). "Cells positive for CD3 and CD5 were also seen mainly in the type B area in type AB thymoma." (PMID 28095872, 2017). "Pathology examination of thymoma on 9 October confirmed malignant thymoma (type B2) with CD3 (+), CD5 (+), and Ki67 (+, 80%) staining." (PMID 40078295, 2025). "Results for CD117, CD5, BAP1, MTAP, and TdT are similar to those previously published, as 32 out of 37 carcinomas and all thymomas in the present study were included in the prior study." (PMID 37190202, 2023). "The expression of CD5, KIT (CD117), EMA (MUC1), and EZH2 is frequently observed in thymic SCCs (75–85%), but is rarely expressed in thymomas (usually <5%)." (PMID 34069513, 2021). "Small stromal lymphoid aggregates containing mature T lymphocytes (CD3+, CD5+, CD1a-, CD99-, Ki67 proliferation index <10%) and CD20+ B lymphocytes were observed in all B2 and B3 thymomas." (PMID 17498299, 2007). "POU2F3 (≥10% hotspot staining), CD117, and CD5 staining was seen in 51%, 86%, and 35% of carcinomas, respectively, and in none of the type A thymomas or micronodular thymomas with lymphoid stroma that were tested." (PMID 37190202, 2023). "In thymoma, lymphocytes can be identified by CD3, CD5, CD20, CD1α, and TdT." (PMID 36797681, 2023). "Although CD5 has been considered a good marker for thymic carcinoma, such marker can also show positive staining in atypical thymoma, some conventional thymomas, and other carcinomas of non-thymic origin." (PMID 35463355, 2022). "However, differential diagnosis for type B3 thymoma is sometimes challenging, even with established markers for TSQCC, including KIT and CD5, which are expressed in ~ 80% of TSQCCs and ~ 3% of thymomas." (PMID 32704057, 2020). "KIT (also known as CD117) and CD5 are established diagnostic markers for TSQCC and are almost always negative in thymoma, with some exceptions." (PMID 32704057, 2020). "The tumor expressed the typical keratin 19 positivity of thymoma; no CD5 or CD117 positive EC were found." (PMID 25105128, 2014). "The KIT-/CD5-positive type B3 thymoma was negative for PRAME." (PMID 32704057, 2020). "Previous studies showed that epithelial cells in B3 thymomas are negative for CD5." (PMID 17498299, 2007).
thymoma (continued). "Hence, human CD5-negative B cells may be suggestive of an in vitro activated population after exposure to phorbol-myristic acetate (PMA) or EL4 thymoma cells, which turn into CD5-positive cells." (PMID 38179278, 2023). "Type B2 and B3 thymomas showed a similar immunophenotype with a variable CK7 expression, and immature intratumoral non-neoplastic T lymphocytes (CD3+, CD5+, CD1a+, CD99+; Ki67 proliferation index >80%)." (PMID 17498299, 2007). "In type B1 thymomas, neoplastic epithelial cells showed expression of EMA and CK7 at the stromal interface, and were consistently CD20, CK20, CD5, and vimentin negative." (PMID 17498299, 2007). "No cases of type B3 thymoma showed simultaneous positivity for PRAME, KIT, and CD5." (PMID 32704057, 2020). "In addition, PRAME-positive thymomas are always KIT- and CD5-negative." (PMID 32704057, 2020).
acute lymphoblastic leukemia (17 papers, 2014 to 2025). Leukemia with an acute onset, characterized by the presence of lymphoblasts in the bone marrow and the peripheral blood. "CD5 CAR-NK cells can be used to accurately recognize CD5+ tumor cells and prolong T-cell acute lymphoblastic leukemia (T-ALL) xenograft mouse survival." (PMID 35410257, 2022). "The novel biosensing platforms based on glass/ZnO NRs/anti-CD5 were tested towards the human T-lymphoblast cell line MOLT-4 derived from patients with acute lymphoblastic leukemia." (PMID 32664437, 2020). "Hence, the intrinsic cytotoxicity of these cells are redirected towards CD5+ T cell acute lymphoblastic leukemia (T-ALL) cell lines (although such antitumor activity is much weaker when compared to CD19-NSCAR γδ T cells against CD19+ B-ALL cell lines)." (PMID 38665921, 2024). "For each co-culture, CD4CAR or vector control NK-92 effector cells were incubated with tumor cells that were comprised of equal numbers of on-target CD4+ cells, CFSE-stained KARPAS-299 or CFSE-stained CCRF-CEM, and “off-target” CMTMR-stained CD4-, CD5+ MOLT4 acute lymphoblastic leukemia cells." (PMID 29348865, 2017). "After completing the functional validation of CD5 CAR-T cells in vitro, we established a mouse tumor model of T cell acute lymphoblastic leukemia (T-ALL) by tail intravenous injection of CCRF-CEM-ffLuc cells to verify the in vivo efficacy of CD5 CAR-T cells." (PMID 34274536, 2021). "CD5 expression is detected in approximately 80% of T-cell acute lymphoblastic leukemia (T-ALL) and lymphoma, as well as in some B-cell lymphomas." (PMID 30891427, 2019). "CD5 is highly expressed in T cell acute lymphoblastic leukemia (T-ALL) and peripheral T cell lymphoma." (PMID 28488245, 2017). "Moreover, a CD5+ T cell acute lymphoblastic leukemia (T-ALL) mouse model was established and used to assess the efficacy of CD5-CAR NK immunotherapy in vivo." (PMID 31097020, 2019). "Studies have explored CD5-CAR-NK cells and CD7-CAR-NK cells for T-cell acute lymphoblastic leukemia (T-ALL) treatment and FLT3-CAR-NK cells in B-cell acute lymphoblastic leukemia (B-ALL)." (PMID 39007146, 2024). "In the realm of T‐cell acute lymphoblastic leukemia (T‐ALL) targets, CD5 stands out as a potentially excellent candidate for T‐cell‐based CAR therapy, due to its distinct expression on the surface of malignant T‐ALL cells." (PMID 39013083, 2024).
colitis (16 papers, 2016 to 2025). Inflammation of the colon. "Our discovery that CD5 KD caused T cell-dependent wasting disease associated with gut immune dysregulation prompted us to ask if the loss of CD5 would exacerbate colitis in experimental models for inflammatory bowel disease (IBD)." (PMID 35720357, 2022). "HucMSC prevents experimental colitis by increasing the number of CD5+ B cells and CD5+Bregs that produce IL-10, and restores Treg/Th17/Th1 imbalances." (PMID 39185411, 2024). "Recent study in a TNBS-induced colitis mice model, human UC-MSCs transplantation protected against experimental colitis by promoting CD5 + B cells and IL-10-secreting CD5 + regulatory B cells (Bregs)." (PMID 36707899, 2023). "Loss of CD5 in NOD mice caused spontaneous wasting disease and severely exacerbated experimental colitis." (PMID 35720357, 2022). "The two mouse lines showed opposite results regarding body weight loss and disease activity index (DAI) changes following DSS-induced colitis, thus supporting Cd5 and Cd6 expression involvement in the pathophysiology of this experimental IBD model." (PMID 36211446, 2022). "We concluded that CD5 KD modifies intestinal T cell activity thereby severely exacerbating induced colitis." (PMID 35720357, 2022). "The observation that both CD5- and CD6-deficient mice differ in their response to DSS-induced colitis further supports their involvement in IBD." (PMID 36211446, 2022). "To this end, we first analyzed the impact of Cd5 and Cd6 deficiency on dextran sulphate sodium (DSS)-induced colitis, an experimental model of human IBD." (PMID 36211446, 2022). "IL-17A was shown to be a key cytokine in colitis, further supporting our hypothesis that the increase in IL-17A secretion by CD5-deficient T cells, secondary to increased Stat3 phosphorylation, is causal for the disease phenotypes we observed in CD5 KD NOD mice." (PMID 35720357, 2022). "To evaluate if the increased severity of experimental colitis in CD5 KDdox mice derived from altered thymic selection, we repeated DSS-colitis experiments in mice thymectomized prior to dox treatment." (PMID 35720357, 2022). "Again, CD5 inhibition exacerbated colitis in this adoptive transfer model that is comparatively mild in the NOD strain." (PMID 35720357, 2022). "After colitis induction, we were able to detect significantly increased numbers of CD5- CD11b+ B cells, which showed marked proliferation (Ki67+ cells) in colorectal LP and PPs but not in the peritoneal cavity (data not shown)." (PMID 34804004, 2021). "We previously showed that hMSCs alleviated experimental colitis, altered the imbalances of Treg/Th1/Th17 cells, and strikingly increased the number of IL-10-producing CD5+ Breg cells." (PMID 31367246, 2019). "On the other hand, ERCs increased the production of IL-10 and the proportion of CD1d+CD5+ Bregs from colitis mice, an important source of IL-10." (PMID 29784012, 2018). "To examine the direct effect of Bregs in ERC-based therapy, we isolated CD1d+CD5+ Bregs from the spleen of ERC-treated colitis mice to perform adoptive transfer, which is an important IL-10 source." (PMID 29784012, 2018). "Since splenic and PerC CD5+ B cells are protective against colitis, we examined the relative production levels of the anti-inflammatory cytokine IL-10 in TLR-stimulated colonic LP CD5+ and CD5- B cells in vitro." (PMID 26727001, 2016). "HUC-MSCs protected against experimental colitis by boosting the numbers of CD5+ B cells and IL-10-producing CD5+ Bregs, and correcting Treg/Th17/Th1 imbalances." (PMID 27515534, 2016). "Furthermore, hUC-MSCs increase the number of CD5+ Breg cells, which in turn suppress T cell proliferation and promote IL-10 production to protect against experimental colitis." (PMID 40433382, 2025). "CD5 KD increased the severity of colitis in the dextran sodium sulfate (DSS)-induced colitis model." (PMID 35720357, 2022).